USP7 (ubiquitin specific peptidase 7)
Diseases named in the same sentence as USP7 in open-access papers (continued):
Sharing a sentence is not in itself a finding about the gene and the disease.
cancer (continued). "Therefore, accumulated studies have suggested that USP7 is a promising target for cancer therapy and thus several small-molecule compounds, such as HBX 41,108, and P5091, has been developed to inhibit the enzymatic activity of USP7 and showed promising antitumor functions in various cancer models." (PMID 34580281, 2021). "Moreover, USP7 with aberrant expression levels and abnormal activity also correlates with cancers." (PMID 34869041, 2021). "Additionally, it will also be necessary to clarify whether the strategy of targeting USP7 to overcome cancer therapy resistance is beneficial for all cancer types or may have certain specificity." (PMID 33967786, 2021). "Although the use of small molecule USP7 inhibitors may therefore be context dependent, anti-cancer efficacy has been reported in several pre-clinical models making it an attractive target in cancer therapy." (PMID 34209840, 2021). "However, the underlying mechanism for the repressive function of USP7 in cancer cell progression was not clearly investigated." (PMID 34580281, 2021). "Thus, USP7 inhibition has become a promising strategy for cancer therapy." (PMID 34580281, 2021). "Therefore, given the suppressive functions of USP7 inhibitors in regulating Foxp3+Treg cells, USP7 could be a potential target in cancer immunotherapy." (PMID 34869041, 2021). "Further analyses may be required to determine this USP7-SMAD/TGFβ pathway in other cancer types." (PMID 34580281, 2021). "Furthermore, our study illustrates the dosage dependence exhibited by haploinsufficient tumor suppressors like USP7, cautioning that while complete inhibition leads to cancer cell death, partial inhibition with small molecules might promote tumor cell growth." (PMID 33664368, 2021). "Moreover, USP7 with aberrant expression levels and abnormal activity are found in cancers." (PMID 34869041, 2021). "Dysregulation of these processes mediated by USP7 may contribute to many diseases, such as cancers." (PMID 34869041, 2021). "Given that paclitaxel-resistant cancer has resistance to mitotic catastrophe, and depletion of USP7 induces mitotic defects and mitotic catastrophe, we next wanted to investigate whether targeting USP7 induces apoptosis in paclitaxel-resistant cancer." (PMID 33207738, 2020). "Therefore, we suggest USP7 is a promising target for cancer therapy, and combination therapy with inhibitors of PLK1 and USP7 may be valuable for treating paclitaxel-resistant cancers, because of their strong synergism." (PMID 33207738, 2020). "Also, it remains to be tested whether the positive feedback regulation of ECT2 and USP7 is applicable for other types of cancer." (PMID 32929379, 2020). "In addition, USP7 is also involved in the regulation of MDM2 in cancer cells." (PMID 33061808, 2020). "Such co-treatment may be particularly effective in cancers that overexpress USP7." (PMID 32850836, 2020). "Thus, HDAC and USP7 inhibitors can be applied in combination for cancer treatment." (PMID 31114498, 2019). "Similarly, the overexpression of USP7 that has been reported in many cancer cells may also induce their proliferation by upregulating KIF20B and promoting cytokinesis." (PMID 30804394, 2019).
cancer (continued). "By changing tumor suppressors' cellular compartmentalization and protein levels, USP7 plays an essential and direct role in tumorigenesis, while its inhibition offers the challenging therapeutic options to reactivate tumor suppressive functions and trigger cancer selective apoptotic response." (PMID 28418900, 2017). "Therefore, USP7 is an attractive drug target for cancer therapy." (PMID 27780924, 2016). "Consequently, Usp7 inhibition was reported to inhibit cancer cell growth and increase apoptosis." (PMID 25962961, 2015). "Using proteomics and ubiquitinomics, we show that USP9X targets distinct substrates compared to USP7, yet the substrate profile of USP9X varies significantly across cancer cell lines." (PMID 41946992, 2026). "From other cancers it is also reported that besides USP28, the deubiquitinases USP7, USP8, USP10 and USP11 interact with NICD and regulate NOTCH1 signaling." (PMID 40456839, 2025). "This compound is one of the most promising PROTACs for USP7 (IC50 = 1.6 ± 0.3 μM), consistently showing an activity in USP7-dependent cancer cells." (PMID 41157055, 2025). "Deubiquitinating enzyme USP7, also known as HAUSP, influences tumor survival and progression by stabilizing key proteins in various cancers." (PMID 40389405, 2025). "The identification of USP7 as a key regulator of DDR1 and the potential development of USP7 inhibitors open new therapeutic avenues for targeting the USP7-DDR1 axis in cancer treatment." (PMID 40713963, 2025). "Various USP7 inhibitors have been explored as potential anti-cancer treatments and the novel allosteric DUB activator (MS-8) specific for USP7 has been reported in the companion manuscript." (PMID 40166258, 2025). "On the other hand, a reduced interaction between USP7 and SIRT7 has been observed in different malignancies, thus promoting gluconeogenesis and proliferation in cancer cells." (PMID 41157055, 2025). "Taken together, our findings identify USP7 as a novel deubiquitinating enzyme of LRRK2 that positively regulates its stability and plays an oncogenic role in AML, with implications for AML cancer progression and potential therapeutic targets." (PMID 40907896, 2025). "The protein network of unique cancer cell genes in the “cancer cells_vs_all-PDAC” group exhibited top 10 hub genes, including H4C6 (HIST1H4A or HIST1H4C), MYC, H3C12 (HIST1H3A or HIST1H3D), DDX21, USP7, RFC4, APEX1, CDK9, H2BC9 (HIST1H2BH), and NOP2." (PMID 40906153, 2025). "To further explore the USP7‐dependent, MDM2‐independent mechanism of action in fibroblasts, we performed a differential gene expression analysis in cancer cells versus fibroblasts." (PMID 38602256, 2024). "Previous studies have connected USPs, such as USP7, USP21, USP22, USP33, USP39, USP54, and others, to carcinogenesis in several cancer types." (PMID 38613804, 2024). "In this study, we found that USP7 bound to DICER but surprisingly down‐regulated its protein level in the nucleus, which impacted DNA damage response (DDR) and cancer progression." (PMID 37867415, 2024). "The patients with high‐mRNA expression levels of either USP7 or MDM2 had a short survival period and obvious cancer‐promoting characteristics, while patients with high expression levels of DICER had longer survival and cancer suppression characteristics." (PMID 37867415, 2024). "USP7 can reduce the levels of the endonuclease DICER, thereby impairing the response to DNA damage and facilitating cancer progression." (PMID 39767641, 2024). "The USP7 gene lies directly adjacent to C16orf72/HAPSTR1 and both genes are commonly co-amplified in up to 7.6% of cancers as well as being co-gained in up to 53% of cases (p < 0.001)." (PMID 38580884, 2024).
cancer (continued). "Inhibiting USP7 promotes CCDC6 degradation, diminishes γH2AX levels, and markedly increases cell sensitivity to PARP inhibitors in various cancer types, including NSCLC, prostate cancer, lung neuroendocrine cancer, bladder cancer, and SOC." (PMID 38702734, 2024). "This activation of USP7 facilitates the deubiquitination of hypoxia-inducible factor (HIF-1α), thereby bestowing resistance to oxaliplatin in cancer cells." (PMID 38702734, 2024). "Recent findings disclose a direct interaction between USP7 and PLK1, with both showing overexpression in paclitaxel-resistant cancer cells." (PMID 38702734, 2024). "USP7 and PLK inhibitors show strong synergistic effects and hold promise for the treatment of paclitaxel-resistant cancers." (PMID 39767641, 2024). "USP7 is a deubiquitinase that contains a USP domain, and is aberrantly expressed in several human cancers." (PMID 37415977, 2023). "A variety of DUB inhibitors have been verified to be effective in malignant tumors, especially those targeting USP1, USP7, and UPS14, displaying great potential for clinical application, such as ML323, SJB3-019A, KSQ-4279, Compound 4, FT671 and VLX1570." (PMID 37369659, 2023). "By Western blot analysis, we showed that MDM2 was slightly decreased in both parental and USP22-Ko A549 cancer cells, while USP22 was significantly upregulated by P5091 treatment, which confirms that P5091 effectively inhibited USP7 deubiquitinase activity." (PMID 37946202, 2023). "Many USPs, including USP2, USP7, USP10, USP22, USP44, and USP9X, have been extensively studied about their role in different types of cancer, which has led to the development of inhibitors for USP1, USP7, USP9X, and USP14." (PMID 37118828, 2023). "Lastly, both USP7 and USP22 are involved in immunosuppression through stabilizing immune check-point inhibitor PD-L1 in cancer and FOXP3 in Tregs, and the significance of this feedback deserves to further study using immune-component cancer model." (PMID 37946202, 2023). "The Transwell assays showed that overexpression of USP7 promotes NSCLC cell migration in both cell lines, which was consistent with the previous finding that c‐Abl contributes to cancer metastasis." (PMID 38082439, 2023). "To verify the pro‐cancer activity of USP7 in NSCLC, we evaluated USP7 in NSCLC growth, metastasis and invasion." (PMID 38082439, 2023). "We found that the USP7-SAMHD1 axis contribute to the DDR and chemotherapy insensitivity of cancer cells." (PMID 37081042, 2023). "Several inhibitors have been verified as effective in battling malignant tumors, especially those targeting USP1, USP7 and USP14, which display great potential for clinical application." (PMID 37369659, 2023). "USP7 inhibitor treatment further suppresses in vivo angiogenesis and tumor growth and induced more apoptosis in USP22-Ko cancer xenografts." (PMID 37946202, 2023). "On the other hand, several deubiquitinating enzymes, including ubiquitin-specific peptidase 7 (USP7), USP22, OTUB1, and CSN5, stabilize PD-L1 protein in cancer cells." (PMID 38038129, 2023).
cancer (continued). "The deubiquitinating enzyme ubiquitin-specific protease 7 (USP7), also known as HAUSP, has been identified as an oncogene with essential roles in tumorigenesis and therapeutic resistance for a number of cancer types." (PMID 36694209, 2023). "Multiple deubiquitinating enzymes, including USP1, USP7, and USP10, have been reported to play a regulatory role in the development of various cancers." (PMID 37821462, 2023). "Attesting to the function, both USP7 and SAMHD1 proteins were highly expressed in human carcinomas of various organs and their expressions were positively correlated." (PMID 37081042, 2023). "USP7 inhibition reduced the activity of DNMT1, which had a detrimental impact on cancer cell survival." (PMID 36428632, 2022). "HAUSP/USP7, USP10, USP11, USP13, OTUD3, and Ataxin-3 have all been recently identified as PTEN DUBs that control PTEN activity in different cancer-specific contexts." (PMID 36385557, 2022). "Growing evidence suggests that combining USP7 inhibitors with immunotherapies such as anti-PD1 or anti-CTLA4 antibodies, and cancer vaccines has the potential to significantly increase antitumor immune responses." (PMID 36428632, 2022). "Complementarily, correlation analyses of USP7 expression and Hippo-YAP/TAZ cancer signatures revealed that its mRNA abundance was significantly correlated with three previously reported Hippo-YAP/TAZ signatures using TCGA-HNSC dataset (p < 0.05)." (PMID 35931679, 2022). "Another novel substrate of USP7 is a histone demethylase PHF8, whose upregulation was shown to be involved in the development and progression of gastric cancer and other malignant tumors." (PMID 34575114, 2021). "Genome-wide analyses further identified that USP7 is specifically required for the transcriptional activation of SMAD3, which is involved in repressing cancer cell proliferation." (PMID 34580281, 2021). "Treatment with P5901 or depletion of USP7 destabilizes PLK1, the master mitotic regulator and a potential therapeutic target for cancer." (PMID 33919439, 2021). "In the last decade, elucidating the role of many USPs, such as USP2, USP7, USP10, USP22, USP44, USP9X, and USP14, in different cancers led to the development of inhibitors for USP7, USP14, USP1, and USP9X." (PMID 34758854, 2021). "USP family members play different functions in cancer, and most of them, such as USP1, USP2, USP7, USP14, and USP17, contribute to cancer promotion." (PMID 33619866, 2021). "Combined treatment with USP7 and EZH2 inhibitors has been shown to reduce the migration and invasion of cancer cells." (PMID 34869041, 2021). "Our study illustrates the dosage dependence exhibited by haploinsufficient tumor suppressors like USP7, cautioning that partial inhibition of USP7 with small molecules might result in increased tumor cell growth, even though complete inhibition of this deubiquitinase leads to cancer cell death." (PMID 33664368, 2021).
cancer (continued). "Immunohistochemical staining (IHC) analysis demonstrated the clear upregulation of USP7 and EZH2 accompanied by the downregulation of FOXO1 in these cancer tissues compared to the normal tissues." (PMID 33849069, 2021). "High USP7/HAUSP expression predicted unfavorable prognosis of cancer patients, especially those with epithelial ovarian cancer (EOC), suggesting that USP7/HAUSP is a critical regulator of Hh signaling and potential therapeutic target for Hh-related cancers." (PMID 34948134, 2021). "For example, the USP7 inhibitors, GEN6776, FT671, and FT827 can repress cancer growth and metastasis." (PMID 33846536, 2021). "Most tumor specimens showed higher expression of PHGDH, USP7, and CTGF compared with the matched para-carcinoma tissues." (PMID 34055773, 2021). "We also collected primary CAFs isolated from mouse tumors, and it is clearly shown that knockdown of USP7 decreased hnRNPA1 protein levels; and the suppression of each of the three genes in CAFs lead to ALOX15 up-regulation in cancer cells." (PMID 32106859, 2020). "USP7 is one of the most studied and best characterized DUB for its implication in different human diseases and in a wide spectrum of human cancers." (PMID 32531973, 2020). "P22077 and HBX19818, which was originally reported as an inhibitor of USP7, inhibit USP10 deubiquitinating activity, which produces anti-cancer activity." (PMID 33158118, 2020). "Treatment of cisplatin relatively promoted the expression of USP7/hnRNPA1 in CAFs, as well as ALOX15 in cancer cells, but the mRNA of ALOX15 remained little changed." (PMID 32106859, 2020). "Recently, more potent and selective USP7 inhibitors, including FT671, GNE6776, and XL-188, were described with superior activity in MM and other cancer types." (PMID 33327527, 2020). "A working model summarizes that in cancer cells, EZH2 recruits USP7 and interacts with other proteins, stabilizes these proteins, thereby repressing the expression of neuron-differentiation genes." (PMID 31130994, 2019). "Both USP7 and PLK1 have been considered bona fide cancer targets, and USP7 or PLK1 inhibitors have been developed to experimentally treat different cancer types or to re-sensitize cancer cells to overcome therapeutic resistance." (PMID 31730000, 2019). "Hence, USP7 may be a promising therapeutic target for the treatment of cancer." (PMID 31114498, 2019). "Both USP7 and PLK1 were overexpressed in taxane-resistant cancer cells, and negatively correlated with the MP scores in tumor tissues." (PMID 31730000, 2019). "USP7 and PLK1 have strong clinical relevance, being overexpressed in tumor cells in a many cancer types." (PMID 31730000, 2019).